MIF (macrophage migration inhibitory factor)
Diseases named in the same sentence as MIF in open-access papers (continued):
Sharing a sentence is not in itself a finding about the gene and the disease.
IgG4-related diseases (1 paper, 2023). "Moreover, MIF or BAFF pathways, common in SLE and IgG4-related diseases, were not increased." (PMID 37373158, 2023).
ileitis (1 paper, 2011). "Our results also implies a MIF-dependent pathogenic role of IL-22 in T. gondii-induced ileitis." (PMID 21977228, 2011). "Since both cytokines upregulate MMP-9 expression, it is possible that MIF regulates tissue remodeling in T. gondii-induced ileitis through a TGF-β/MMP-9 pathway." (PMID 21977228, 2011). "Together, these results indicate that MIF is involved in the response to T. gondii infection of the small intestine, increasing the ileitis and the systemic inflammatory response." (PMID 21977228, 2011). "In conclusion, we demonstrated that MIF participates in the pathogenesis of natural T. gondii infection in C57BL/6 mice, promoting an intense ileitis and a robust systemic inflammatory response that resulted in poor outcome during the acute phase." (PMID 21977228, 2011). "Our results showed that MIF mediated T. gondii-induced ileitis does not affect IL-4 and increase IL-10 and TGF-β expression." (PMID 21977228, 2011).
intracranial aneurysm (1 paper, 2024). "Conversely, our result in reverse MR indicated that multiple inflammatory biomarkers, including IL-10, RANTES, MIF, and GRO-alpha, were suggestively affected by intracranial aneurysm and its subtypes." (PMID 38173028, 2024).
ischemia reperfusion injury (1 paper, 2022). Adverse functional, metabolic, or structural changes in ischemic tissues resulting from the restoration of blood flow to the tissue (reperfusion), including swelling; hemorrhage; necrosis; and damage from free radicals. "Recent studies have demonstrated that MIF can be expressed in renal tubular epithelial cells, especially in the tubules with ischemia-reperfusion injury, suggesting that there is a pathological link between MIF and AKI." (PMID 36117692, 2022).
ischemic disease (1 paper, 2024). Lack of blood supply to an area of the body, resulting in impairment of tissue oxygenation. "This includes investigating the chemotactic response mediated by MIF and optimizing the MIF dosage in EPC-CM for its application in ischemic diseases." (PMID 39543689, 2024).
knee osteoarthritis (1 paper, 2025). "An individual’s milieu of inflammatory cytokines may contribute to the development and severity of knee osteoarthritis, where higher concentrations of serum TNF-α and macrophage migration inhibitory factor (MIF) are associated with increased severity." (PMID 40219030, 2025).
lepromatous leprosy (1 paper, 2018). A chronic communicable infection which is a principal or polar form of leprosy. "Ranking of lepromatous leprosy (LL) patients and healthy skin (HSk) according to their score of migration inhibitory factor (MIF) staining." (PMID 29487601, 2018).
leprosy (1 paper, 2018). Leprosy is a chronic infectious disease affecting primarily the skin and peripheral nervous system. "It is important to pursue paucibacillary cases to better detail the role of MIF in leprosy; in particular, the study of MIF in indeterminate leprosy results of particular interest due to the functions of MIF in innate immunity." (PMID 29487601, 2018). "This paradoxical observation relates the inflammatory cytokine MIF with the anti-inflammatory LL pole and is suggestive of an important role for MIF in this spectrum of leprosy." (PMID 29487601, 2018). "To obtain more information about MIF role in leprosy, we examined skin biopsies by IHC to inquire about its cellular and tissular localization." (PMID 29487601, 2018). "Further description of MIF and CD74, as well as the possibly involved signaling pathways, namely, PI3K, MAPK could yield valuable insight into leprosy immunopathology." (PMID 29487601, 2018). "Given that 80% of new cases of leprosy Mexico are multibacillary cases, our observations of MIF and CD74 are limited to LL patients without treatment." (PMID 29487601, 2018). "Since MIF expression is not different between LL skin and HSk, we measured CD74 expression to determinate if it is involved in leprosy lesions." (PMID 29487601, 2018).
lipid metabolic disorders (1 paper, 2022). "Since MIF is also a key factor in lipid metabolism disturbance, we hypothesized that MIF signaling might be important for hypoxia-induced lipid metabolic disorders." (PMID 36042480, 2022).
lipodystrophy (1 paper, 2024). A congenital or acquired disorder characterized by abnormal loss or redistribution of the adipose tissue in the body. "It is possible that HSL mutations during development cause some degree of loss of adipose cell number and lipodystrophy, which does not occur with post-developmental MIF-mediated loss of HSL during HFD." (PMID 37935315, 2024).
Listeria monocytogenes infection (1 paper, 2010). "Interestingly, during murine Listeria monocytogenes infection, the elimination of bacteria from the spleen and liver was not affected by anti-MIF antibody although this treatment was able to rescue mice from lethal infection." (PMID 20169062, 2010).
lobular carcinomas (1 paper, 2014). "The intensity of immunohistochemical staining for MIF was assessed in tumor-free breast tissues (tumor-free, n=16) and in invasive ductal and lobular carcinomas (cancer, n= 96)." (PMID 24939415, 2014).
lung tumors (1 paper, 2018). "However, expression levels of downstream markers TPM-1, TOM-1, CRK, fibulin-2, MIF, and EFNA-3 were greater in the lung tumors than in non-tumor specimens only in patients without COPD." (PMID 29371906, 2018).
Lymphatic Metastasis (1 paper, 2021). Transfer of a neoplasm from its primary site to lymph nodes or to distant parts of the body by way of the lymphatic system. "We found that the MIF expression of patients with lymphatic metastasis was significantly higher than patients without lymphatic metastasis." (PMID 35036405, 2021).
lymphedema (1 paper, 2023). Excess fluid collection in tissues, causing swelling. "Interestingly, these interactions also increased in PACs of the lymphedema, whereas the increased MIF signal of PACs was found to be a distinct characteristic of CrF." (PMID 38111581, 2023).
male infertility (1 paper, 2020). The inability of the male to effect fertilization of an ovum after a specified period of unprotected intercourse. "Increased concentrations of IL-18 and MIF have previously been implicated in male infertility and reduced sperm motility." (PMID 36304709, 2020).
mammary adenocarcinoma (1 paper, 2009). "In fact, it was suggested that MIF is a determinant of the M1-subtype of TAMs and that mammary adenocarcinoma cells lead to MIF ablation in M1-TAMs, inducing a switch towards M2 polarization." (PMID 19602265, 2009).
mesangial sclerosis (1 paper, 2016). "In addition, a transgene of MIF induces podocyte injury and progressive mesangial sclerosis in the mouse kidney." (PMID 27313397, 2016).
Mitral regurgitation (1 paper, 2025). An abnormality of the mitral valve characterized by insufficiency or incompetence of the mitral valve resulting in retrograde leaking of blood through the mitral valve upon ventricular contraction. "The result was similar but not identical for MIF, which showed a positive correlation with mitral regurgitation, leukocyte counts, and CK, and a negative one for LVEF and the glomerular filtration rate (GFR)." (PMID 40055309, 2025).
nephrotic syndrome (1 paper, 2026). A collection of symptoms that include severe edema, proteinuria, and hypoalbuminemia; it is indicative of renal dysfunction. "Urinary MIF/creatinine levels were significantly elevated in steroid-resistant nephrotic syndrome (SRNS) relative to in steroid-sensitive nephrotic syndrome (SSNS) and controls (p < 0.001)." (PMID 40968277, 2026).
obstructive sleep apnea (1 paper, 2025). "Furthermore, hypoxic conditions, commonly present in AF-related comorbidities such as obstructive sleep apnea, can induce HIF-1α expression in atrial cardiomyocytes, promoting the upregulation of macrophage migration inhibitory factor (MIF)." (PMID 41561130, 2025).
oral mucositis (1 paper, 2023). Inflammation of the mucous membranes of any of the structures in the mouth. "MIF protein, which was reported to correlate to severe oral mucositis, was found to be upregulated as well." (PMID 37384298, 2023).
oropharyngeal carcinoma (1 paper, 2019). Carcinoma, predominantly squamous cell, arising from the epithelial cells of the oropharynx. "The immunohistochemical staining of MIF was examined in two series of 117 cases of oral cavity, and 39 cases of oropharyngeal carcinomas." (PMID 30634708, 2019). "Thus, we have evaluated MIF expression in a series of 156 clinical samples including oral cavity and oropharyngeal carcinomas." (PMID 30634708, 2019).
pancreatic diseases (1 paper, 2021). "There appears to be a compelling role for MIF in pancreatic diseases." (PMID 33776775, 2021).
pancreatic insufficiency (1 paper, 2014). "Patients carrying at least one copy of the 5-repeat MIF-CATT allele were found to have a decreased incidence of P. aeruginosa colonization (defined as the presence of bacteria in the sputum) and a significant reduction in the risk of pancreatic insufficiency." (PMID 25503271, 2014).
parasite (1 paper, 2019). "As intraperitoneal delivery of MIF did not restore resistance to the parasite infection (data not shown), it is likely that localized production and release within the intestinal tract may be required for effective recruitment and activation of tissue macrophages at the site of infection." (PMID 31708913, 2019).
paroxysmal AF (1 paper, 2025). "Specifically, MIF levels are highest in patients with permanent AF, followed by those with persistent AF, and lowest in those with paroxysmal AF." (PMID 41357167, 2025).
peripheral nerve injury (1 paper, 2021). Injury to a peripheral nerve. "A proinflammatory cytokine, macrophage migration inhibitory factor (MIF), downregulates DA release after peripheral nerve injury." (PMID 33510781, 2021).
photokeratitis (1 paper, 2010). Injury to the cornea secondary to ultraviolet light. "In a previous report it was determined that MIF was advantageous for corneal recovery after ultraviolet-induced photokeratitis in mice." (PMID 21152395, 2010).
pituitary deficiency (1 paper, 2023). "MIF is unique in that it is both produced locally in tissues by immune cells counteracting cortisol’s inhibitory effect and excreted systemically as a pituitary hormone in relation to stress It could be speculated that the low levels are related to pituitary deficiency which characterizes PWS." (PMID 37430349, 2023).
polyarthritis (1 paper, 2015). "MIF is associated with the susceptibility but not severity of polyarthritis." (PMID 26469786, 2015).
polycystic ovary syndrome (1 paper, 2015). A disorder that manifests as multiple cysts on the ovaries. "Indeed, circulating MIF levels are two to threefold higher in women with polycystic ovary syndrome (PCOS), an endocrine disorder characterized by elevated levels of androgens." (PMID 26124760, 2015).
Pruritus (1 paper, 2024). Pruritus is an itch or a sensation that makes a person want to scratch. "Our results showed that MIF combined with the PAR2 agonist SLIGRL produced acute pruritus flares, indicating that MIF may also directly mediate itch sensation." (PMID 39416784, 2024). "In conclusion, the release of MIF mediated by PAR2 activation is a crucial process relating to the immune imbalance and pruritus found in HDM-allergic AD model." (PMID 39416784, 2024).
psychosis (1 paper, 2024). "These discoveries underscore the significant roles of miR-29a-3p and MIF in regulating social behavior and suggest that their dysregulation may influence neurobehavioral phenotypes, ultimately contributing to the development of social deficits in individuals with psychosis." (PMID 38645418, 2024).
Pulmonary hemorrhage (1 paper, 2021). Pulmonary hemorrhage is a bleeding within the lungs. "Patients with pulmonary hemorrhage have remarkably higher MIF levels than with other clinical manifestations." (PMID 35237527, 2021).
relapsing-remitting multiple sclerosis (1 paper, 2024). The most common clinical variant of multiple sclerosis, characterized by recurrent acute exacerbations of neurologic dysfunction followed by partial or complete recovery. "In addition, a significant increase in MIF levels was observed in the cerebrospinal fluid of patients with relapsing-remitting multiple sclerosis (RRMS), and circulating MIF levels were higher in patients with progressing disability than those with stable disease." (PMID 38390325, 2024).
Respiratory syncytial virus infection (1 paper, 2022). "Respiratory syncytial virus infection increases Mif MRNA expression in mouse macrophages and inhibition of MIF with ISO-1 (small molecule inhibitor) inhibits RSV-induced release of TNF, MCP-1 and IL-10." (PMID 36110852, 2022).
rhabdomyolysis (1 paper, 2015). Necrosis or disintegration of skeletal muscle often followed by myoglobinuria. "Since there is no information regarding the changes in plasma MIF levels in rhabdomyolysis-associated AKI, the time profile of the plasma MIF level was monitored after the glycerol injection." (PMID 26412311, 2015).
SARS-CoV infection (1 paper, 2021). "Most were upregulated such as PTGES, MIF, CCR7, CXCL6 and CXCL12, which encodes immune cytokines known to be transcriptionally upregulated during SARS-CoV infection." (PMID 34282405, 2021).
septic shock (1 paper, 2016). Shock caused by infection; frequently caused by gram negative bacteria, although some cases have been caused by other bacteria, viruses, fungi, and protozoa; characterized by fever, chills, tachycardia, tachypnea, and hypotension. "In patients who survived septic shock, MIF plasma levels during ICU stay were lower compared to patients who did not survive septic shock." (PMID 27313864, 2016).
severe combined immunodeficiency (1 paper, 2019). Severe combined immunodeficiency (SCID) comprises a group of rare monogenic primary immunodeficiency disorders characterized by a lack of functional peripheral T lymphocytes resulting in early-onset severe respiratory infections and failure to thrive. "First, although we observed no teratogenic effects of MIF-overexpressing MSCs in severe combined immunodeficiency mice in the current study (data not shown), genetically modified MSCs need to be carefully evaluated prior to their application in clinical practice." (PMID 31881006, 2019).
spondyloarthritis (1 paper, 2025). "As seen in SKG mice, human neutrophils from spondyloarthritis subjects produce higher levels of MIF than healthy controls." (PMID 40938333, 2025).
ST Elevation Myocardial Infarction (1 paper, 2022). A myocardial infarction that produces elevation in the ST segments of the ECG. "In a human study of 374 ST-elevation myocardial infarction (STEMI) patients, of all biomarkers measured on admission including troponins, only MIF was correlated with infarct size, ejection fraction, and ventricular volumes on cardiac MRI at the 3-day and 3-month mark." (PMID 35722087, 2022).
Stillbirth (1 paper, 2012). Death of the fetus in utero after at least 22 weeks of gestation. "In addition, elevated intervillous MIF levels are associated with both stillbirth and low birth weight deliveries." (PMID 23272137, 2012). "In this study, higher levels of IVB MIF were associated with stillbirth deliveries and LBW babies irrespective of malaria infection status." (PMID 23272137, 2012). "One possibility is that elevated levels of MIF may directly regulate some biological events related to stillbirth and LBW." (PMID 23272137, 2012). "Therefore, MIF may have a direct role in activating biological pathways that contribute to stillbirths and LBW." (PMID 23272137, 2012). "For example, high levels of MIF (along with other factors such as TNF) can activate the inducible cyclooxygenase (COX)-2 pathway, leading to higher prostaglandin production and potentially other pathways that contribute to stillbirth and LBW." (PMID 23272137, 2012).
subarachnoid hemorrhage (1 paper, 2023). A serious neurological disorder characterized by intracranial hemorrhage into the subarachnoid space. "For instance, both elevated MIF and FABP3 have been previously shown to be linked to worse clinical outcome after subarachnoid hemorrhage and brain injury." (PMID 37277809, 2023).
systemic vasculitis (1 paper, 2010). "Collectively, these findings suggest dysregulated orchestration of the activities of MIF, adhesion molecules, and cytokines expressed by ECs and/or leukocytes plays a crucial role in the development of systemic vasculitis (e.g., MPA and RV)." (PMID 22046508, 2010). "We recently showed that serum MIF levels are significantly increased in some patients with systemic vasculitis." (PMID 22046508, 2010).
tauopathy (1 paper, 2015). Neurodegenerative disorders involving deposition of abnormal tau protein isoforms (tau proteins) in neurons and glial cells in the brain. "Based on these findings, we postulate that MIF plays a role in tauopathy through activation of astrocytes." (PMID 26382037, 2015). "Despite these findings, a correlation between MIF and tauopathy has not been established experimentally." (PMID 26382037, 2015).
tendinopathy (1 paper, 2018). "However, innervation seems to play a more important role in the acute situation, as acute ruptured tendons expressed higher amounts of PGP9.5 and MIF compared to tendinopathy, and chronic/intact tendons, respectively." (PMID 29385715, 2018). "The expression of macrophage migration inhibitory factor (MIF), a nerve regeneration marker, and PGP9.5, a general nerve marker, was significantly increased in acute ruptures compared to the intact and chronic ruptures or tendinopathy group, respectively." (PMID 29385715, 2018).
teratoma (1 paper, 2020). A non-seminomatous germ cell tumor characterized by the presence of various tissues which correspond to the different germinal layers (endoderm, mesoderm, and ectoderm). "Macrophage-derived MIF was later reported to both sufficient and necessary for driving the angiogenic contribution of bone-marrow-derived macrophages to teratoma formation in mice suggesting a dominant functional role for monocyte/macrophage-derived MIF in M2 macrophage functional polarization." (PMID 33324425, 2020).
thoracic tumors (1 paper, 2018). "In order to assess the effect of the MIF/CD74 pathway in the development of MPM, we derived a new human MPM cell line expressing MIF, CD74, and CD44 and able to generate orthotopic intra-thoracic tumors." (PMID 29949929, 2018).
thyroid tumor (1 paper, 2022). A benign or malignant neoplasm affecting the thyroid gland. "We explored the cell-cell interaction in thyroid tumor environment and found that fibroblasts could widely interact with other immune cells via Macrophage Migratory Inhibition Factor (MIF) signaling pathway." (PMID 36387901, 2022).
tubular adenocarcinoma (1 paper, 2015). An infiltrating adenocarcinoma in which the malignant cells form tubular structures. "We also used immunohistochemistry to examine the MIF expression in paired samples of tubular adenocarcinoma from 29 patients with CRC in primary tumors and liver metastases." (PMID 26087187, 2015).
unstable angina (1 paper, 2013). "At admission (average 3 h after onset of symptoms), plasma level of MIF was 3.2-fold higher than the two control groups, healthy control and stable angina." (PMID 24098445, 2013). "We recruited 15 patients with MI, 10 patients with stable angina and 10 healthy volunteers and measured temporal changes of MIF in plasma." (PMID 24098445, 2013). "Elevated plasma levels of MIF were also reported in patients with MI, but not in those with unstable angina, suggesting that MIF may be released from necrotic cardiomyocytes." (PMID 24098445, 2013).